PMEPA1 (prostate transmembrane protein, androgen induced 1)
Diseases named in the same sentence as PMEPA1 in open-access papers (continued):
Sharing a sentence is not in itself a finding about the gene and the disease.
infection (1 paper, 2022). The state of being infected such as from the introduction of a foreign agent such as serum, vaccine, antigenic substance or organism. "Interestingly, significantly elevated expression of six above-mentioned associated genes (Pmepa1, Mamstr, Rasip1, Tpm1, Itih4 and Ogdhl) in mice total liver tissues was also observed from the seventh week (S. japonicum spawn in large numbers) after infection." (PMID 35493725, 2022).
PMEPA1 also shares sentences with these, for which no sentence is quoted: renal carcinoma (2 papers); Allergy (1); autosomal dominant polycystic kidney disease (1); biliary tract cancer (1); colorectal tumours (1); gastric tumor (1); Hearing impairment (1); Hydroureter (1); hypospadias (1); infertile (1); intestinal polyp (1); invasive breast carcinoma (1); Kidney Cyst (1); lentivirus infection (1); lung adenocarcinoma (1); oral cancer (1); ovarian tumor (1); Pan (1); polycystic kidney (1); psychiatric disorder (1); thoracic aortic aneurysm (1).